ZNF705A (zinc finger protein 705A)
Description:
May be involved in transcriptional regulation.
Synonyms: FLJ16353
Tractability: No criterion of Open Targets' tractability assessment is met for any kind of drug.
Gene: Protein-coding gene on chromosome 12 (8,157,015 to 8,188,537, forward strand). Ensembl gene ENSG00000196946.
Subcellular location: Nucleus
Pathways (Reactome):
Gene expression (Transcription): Generic Transcription Pathway
Gene Ontology:
Molecular function: DNA-binding transcription factor activity, RNA polymerase II-specific; RNA polymerase II transcription regulatory region sequence-specific DNA binding; sequence-specific double-stranded DNA binding
Biological process: regulation of transcription by RNA polymerase II; regulation of DNA-templated transcription
Cellular component: chromatin; nucleus
Genetic constraint (gnomAD): Loss-of-function variants: 8 observed, 10.69 expected, observed/expected ratio (o/e) 0.75, 90% interval 0.44 to 1.35. The synonymous counts are far from expectation, so gnomAD's model fits this gene poorly and the ratio says little. Missense variants: 233 observed, 319.81 expected, observed/expected ratio (o/e) 0.73, 90% interval 0.65 to 0.81. Synonymous variants: 72 observed, 102.52 expected, observed/expected ratio (o/e) 0.7, 90% interval 0.58 to 0.85.
Homologues: Orthologues: chimpanzee ZNF705A (98% identical), mouse Zfp78 (34% identical), Drosophila melanogaster CG3281 (23% identical), Drosophila melanogaster CG2712 (21% identical), Drosophila melanogaster Phs (20% identical). Paralogues in human: ZNF705D (96% identical), ZNF705B (95% identical), ZNF705G (95% identical), ZNF596 (54% identical), ZFP90 (43% identical), ZNF555 (39% identical), ZNF266 (38% identical), ZNF77 (37% identical), ZNF805 (37% identical), ZNF599 (37% identical), ZNF133 (36% identical), ZNF264 (36% identical), and 50 more.
Diseases named in the same sentence as ZNF705A in open-access papers:
ZNF705A is named in the same sentence as 3 diseases in open-access papers, as found by Europe PMC text mining. Sharing a sentence is not in itself a finding about the gene and the disease. The quoted sentences say what the papers report.
germ cell tumor (1 paper, 2022). A benign or malignant, gonadal or extragonadal neoplasm that originates from germ cells. "ZNF705A was specifically highly expressed in germ cell tumors, which may be potential targets for cancer therapy." (PMID 36405735, 2022).
ZNF705A also shares sentences with these, for which no sentence is quoted: cancer (1 paper); tumor (1).